DLGAP5 (DLG associated protein 5)
Diseases named in the same sentence as DLGAP5 in open-access papers (continued):
Sharing a sentence is not in itself a finding about the gene and the disease.
gastric cancer (4 papers, 2021 to 2025). A primary or metastatic malignant neoplasm involving the stomach. "Nevertheless, in gastric cancer patients, lower expression DLGAP5 patients had poorer OS (P < 0.001), FP (P < 0.001) and PPS (P < 0.001) prognosis." (PMID 34454476, 2021). "Since depletion of NKX6.3 in gastric epithelial cell lines induced CNAs and abnormal expression of SORBS2, SPARCL1, DLGAP5, and CDKN3, we examined NKX6.3 expression and these genes’ CNAs and expression in gastric cancer tissues." (PMID 34893582, 2021). "The expression levels of CDKN3 and DLGAP5 were markedly increased, whereas those of SPARCL1 and SORBS2 were decreased in 60 human gastric cancers." (PMID 34893582, 2021). "In addition, the mRNA expression levels of CDKN3, DLGAP5, SPARCL1, and SORBS2 were positively correlated with CNAs in our gastric cancer samples." (PMID 34893582, 2021).
osteosarcoma (4 papers, 2023 to 2025). A usually aggressive malignant bone-forming mesenchymal neoplasm, predominantly affecting adolescents and young adults. "In osteosarcoma, DLGAP5 has been demonstrated to promote tumor development via the IL-6/JAK2/STAT3 signaling pathway." (PMID 40181976, 2025). "DLGAP5 has been shown to activate the IL-6/JAK2/STAT3 signaling pathway, thereby promoting the proliferation and invasion of osteosarcoma cells." (PMID 37958803, 2023). "It has been shown that DLGAP5 can activate interleukin-6/Janus kinase 2/signal transducer and activator of transcription 3 (IL-6/JAK2/STAT3) signaling pathway thereby promoting the proliferation and invasion of osteosarcoma cells." (PMID 36712920, 2023).
psoriasis (4 papers, 2022 to 2025). An autoimmune condition characterized by red, well-delineated plaques with silvery scales that are usually on the extensor surfaces and scalp. "It is the first time that BUB1B and DLGAP5 have been linked to the onset of psoriasis, though exact mechanisms are yet unknown." (PMID 36185088, 2022). "In psoriasis, the five diagnostic hub genes (KIF4A, DLGAP5, NCAPG, CCNB1, and CEP55) were predominantly expressed in keratinocytes, with significantly higher expression levels in patient samples compared to controls." (PMID 40406126, 2025). "After the identification and validation of DEGs, BUB1B and DLGAP5 were finally found as core genes in the development of psoriasis." (PMID 36185088, 2022). "Additionally, the expression of BUB1B and DLGAP5 in the blood samples of psoriasis patients was also higher than that of normal controls." (PMID 36185088, 2022). "All these results revealed that BUB1B as well as DLGAP5 may bridge the gap between psoriasis and cancers." (PMID 36185088, 2022). "Therefore, upregulation of DLGAP5 may affect the abnormal differentiation of keratinocytes in psoriasis and intestinal epithelial cell repair in CD by enhancing cell proliferation and mitosis regulation." (PMID 40406126, 2025). "In the psoriasis dataset (GSE13355), the AUC values for KIF4A (AUC = 0.99), DLGAP5 (AUC = 1), NCAPG (AUC = 0.99), CCNB1 (AUC = 0.99), and CEP55 (AUC = 0.99) exhibited exceptional diagnostic performance, with all values exceeding 0.7." (PMID 40406126, 2025). "In the psoriasis validation cohort (GSE14905), the AUC values for KIF4A, DLGAP5, NCAPG, CCNB1, and CEP55 were 0.96, 0.97, 0.96, 0.98, and 0.93, respectively." (PMID 40406126, 2025). "This integrative approach highlighted KIF4A, DLGAP5, NCAPG, CCNB1, and CEP55 as key shared biomarkers for both psoriasis and CD." (PMID 40406126, 2025). "The gene expression heatmap showed high expression of core genes (TOP2A, MELK) in psoriasis samples, while DEPDC1B, CCNA2, DLGAP5, NUF2, ASPM were lowly expressed in psoriasis samples." (PMID 38382096, 2024). "We found that core genes (TOP2A, MELK) were highly expressed in psoriasis samples and lowly expressed in normal tissue samples, while DEPDC1B, CCNA2, DLGAP5, NUF2, ASPM were lowly expressed in psoriasis samples." (PMID 38382096, 2024).
colon cancer (3 papers, 2013 to 2024). "p.Val < 0.05) of these hub genes, except for the DLGAP5 gene which was not present in the colon cancer data set." (PMID 39045407, 2024).
lymph node metastasis (3 papers, 2013 to 2024). "Next, we proceeded to explore the relationship between the expression of RHOV, ANLN, PTTG1, DLGAP5, and FAM83A with pathological stage and lymph node metastasis, and the results showed that the transcriptional expression of the five prognostic features progressively increased with the stage." (PMID 39144144, 2024).
neuroblastoma (3 papers, 2012 to 2017). Neuroblastoma (NB) is the most common solid, extracranial childhood tumor. "We identified six genes (DLGAP5, DSCC1, SMO, SNRPD1, SSBP1, and UBE2C) with a vital role in mitosis and these are promising therapeutic targets for neuroblastoma." (PMID 23251412, 2012).
acute myelogenous leukemia (2 papers, 2022 to 2023). "Excluding mesothelioma (MESO) and uveal melanoma (UVM) without corresponding paraneoplastic tissue specimens, the pan-cancer analysis revealed that significant upregulation of DLGAP5 in 30 of 31 cancers compared to paraneoplastic tissue, but downregulation in acute myelogenous leukemia (LAML)." (PMID 36712920, 2023).
female infertility (2 papers, 2023 to 2025). Diminished or absent ability of a female to achieve conception. "Utilizing WES, for the first time, we have identified DLGAP5 as a pathogenic gene responsible for human female infertility with phenotype, characterized by abnormal oocyte maturation and embryo development." (PMID 40416599, 2025). "Furthermore, DLGAP5 knockout in mice causes female infertility, but DLGAP5 is dispensable for normal mouse development." (PMID 36712920, 2023).
thyroid cancer (2 papers, 2018 to 2022). "Expression levels of TRIP13, TPX2, DLGAP5, KIF2C and TTK were associated with shorter disease free survival (DFS) among differentiated thyroid cancer." (PMID 30386706, 2018).
astrocytoma (1 paper, 2021). "In TCGA database, we found that LMNB1 and DLGAP5 were highly expressed in oligodendrogliomas, astrocytoma and GBM." (PMID 33956061, 2021).
colorectal adenocarcinoma (1 paper, 2020). The most common type of colorectal carcinoma. "We found that among the 12 central genes, CCNA2, MAD2L1, DLGAP5, and AURKA were associated with the overall survival of colorectal adenocarcinoma (P < 0.05), and RRM2 and AURKA were associated with disease-free survival of colorectal adenocarcinoma (P < 0.05)." (PMID 33519906, 2020).
dengue (1 paper, 2023). "The GO analysis revealed that the genes BUB1, RRM2, IFI27, DLGAP5, and CEP55 exhibit 4-fold up-regulation in dengue and SD patients however, they exhibit downregulation in CP." (PMID 38076406, 2023).
diabetes (1 paper, 2022). "Nonetheless, none of the expression of ASPM, CDC20, DLGAP5, BUB1B, CDCA8, and NCAPG was related to BMI and diabetes." (PMID 36186000, 2022).
endometriosis (1 paper, 2023). The growth of functional endometrial tissue in anatomic sites outside the uterine body. "In the context of endometriosis research, DLGAP5 may be involved in cellular proliferation and differentiation processes, further influencing the development and progression of the disease." (PMID 38098472, 2023). "However, the precise connection between DLGAP5 and endometriosis has not been fully elucidated to date, and the specific molecular mechanisms require further research." (PMID 38098472, 2023). "Previous research has not studied the impact of DLGAP5 and ADAT on endometriosis." (PMID 38098472, 2023).
melanoma (1 paper, 2025). A malignant, usually aggressive tumor composed of atypical, neoplastic melanocytes. "In contrast, the vehicle samples of cell line M130227 predominantly upregulate factors that indirectly influence MAPK pathway activity through growth factor signaling and cell cycle progression, thereby promoting melanoma aggressiveness (e.g., PGF, CDCA8, DLGAP5, TPX2)." (PMID 41199020, 2025).
oral squamous cell carcinoma (1 paper, 2022). "It was reported Dlgap5 was involved in cell proliferation, differentiation, and migration in oral squamous cell carcinoma." (PMID 35495761, 2022).
ovarian serous cystadenocarcinoma (1 paper, 2021). A malignant serous cystic epithelial neoplasm arising from the ovary. "While DLGAP5 expression showed less consistent relationship with MSI among different tumors, as negative in DLBC (P < 0.05), but positive in OV (Ovarian serous cystadenocarcinoma), PRAD, SARC (Sarcoma), BRCA, COAD, STAD, READ, KICH (all P < 0.05)." (PMID 34454476, 2021).
retinoblastoma (1 paper, 2023). A malignant tumor that originates in the nuclear layer of the retina. "Particularly, TPX2, KIF20A, CENPA, DLGAP5, and LMNB1 of HHOs were significantly enriched by the retinoblastoma (RB) immunity downregulating PD-L1 expression pathway." (PMID 37240068, 2023).
uterine tumors (1 paper, 2021). "Among them, DLGAP5 had the highest mutation rate (> 5 %) in patients with uterine tumors." (PMID 34454476, 2021).
ZIKV infection (1 paper, 2018). "Genes associated with cell differentiation and proliferation, such as BUB1, DLGAP5, PBK and CEP55 (Cluster 3) were upregulated during DENV infection but not ZIKV, while EGR1, HBEGF and MAFB (Cluster 4), were up-regulated at d17 POS during ZIKV infection." (PMID 30596671, 2018).
cancer (62 papers, 2009 to 2025). A tumor composed of atypical neoplastic, often pleomorphic cells that invade other tissues. "DLGAP5 in cancer was also significantly associated with the density of macrophages and CD8+ T cells infiltrating into different tumours." (PMID 39910622, 2025). "Human discs large-associated protein 5 (DLGAP5) is reported to play a pivotal role in regulating the cell cycle and implicate in tumorigenesis and progression of various cancers." (PMID 38414025, 2024). "DLGAP5 is a microtubule-associated protein and is identified to be a prognosis biomarker in various cancers." (PMID 35873497, 2022). "Increased DLGAP5 gene expression has been found in most types of cancers and is associated with poor prognosis." (PMID 35204661, 2022). "As a biomarker, DLG associated protein 5 (DLGAP5) is a potential cell cycle regulator in cancer cell carcinogenesis." (PMID 35873473, 2022). "Cohort and bioinformatic studies have revealed high expression of DLGAP5 and its association with poor OS in numerous cancers." (PMID 36499051, 2022). "Apart from that, in this article, we, for the first time, demonstrated the association of DLGAP5 expression and immune infiltration level of cancer-associated fibroblasts in certain tumors." (PMID 34454476, 2021). "For example, based on the TIDE algorithm, we can detected that the DLGAP5 expression status was negatively correlated with the infiltration level of cancer-associated fibroblasts in BRCA (cor = − 0.182, P = 7.52e−09)." (PMID 34454476, 2021). "DLGAP5 (Discs large homolog associated protein 5) is involved in mitotic spindle assembly, and its overexpression is associated with tumor progression and adverse outcomes in cancer patients, highlighting its role in cell division and potential as a therapeutic target." (PMID 38962012, 2024). "DLGAP5 is strongly correlated with cancer occurrence and poor prognosis across multiple cancer types." (PMID 40181976, 2025). "Elevated DLGAP5 expression correlates with diminished serum-dependent and anchorage-independent growth of cancer cells." (PMID 39100078, 2024). "Next, to capture the expression of DLGAP5 at single-cell resolution and its correlation with cancer functional states in LUAD, we conducted an analysis via CancerSEA database using two GEO datasets: GSE69405 and GSE85534." (PMID 38414025, 2024). "There is a significant correlation between the expression of DLGAP5, which is highly expressed in many cancer types, and poor prognoses in patients with cancer." (PMID 39902297, 2024). "Data from TCGA and GTEx databases showed that DLGAP5 mRNA expression was dramatically upregulated in multiple type of cancer tissues including LUAD." (PMID 38414025, 2024). "Seven BC samples and seven para-cancer tissue samples were collected for IHC assays to verify the DLGAP5 expression." (PMID 37958803, 2023). "Cancer cell line database (CCLE) results revealed that the expression of DLGAP5 in the A549 cell line was at the middle level among all cell lines and was chosen for CCK-8 experiments." (PMID 36983664, 2023). "In recent years, DLGAP5 has been reported to have a dominant role as an oncogene in a variety of cancers." (PMID 36712920, 2023). "The pan-cancer analysis demonstrated that the mRNA expressions of DLGAP5 were higher in nearly all tumors compared with normal controls, except LAML." (PMID 36983664, 2023). "Horning AM and colleagues demonstrated that DLGAP5 played an essential role in cancer cell carcinogenesis." (PMID 35873473, 2022). "All of above data suggested that increased DLGAP5 expression points to poorer prognosis in majority of different cancer types." (PMID 34454476, 2021). "In this study, we initially presented the evidence of the association between DLGAP5 expression and MSI or TMB across all TCGA cancers." (PMID 34454476, 2021). "DLGAP5 is highly expressed in most type of cancers, and there is a significant correlation between the expression of DLGAP5 and the prognosis of cancer patients." (PMID 34454476, 2021).
cancer (continued). "In our research, primarily, we executed pan-cancer analysis of DLGAP5 by the TCGA project and GEO databases." (PMID 34454476, 2021). "Taken together, our unpresented pan-cancer analysis of DLGAP5 provides a relatively integrative understanding of the oncogenic role of DLGAP5 in various tumors." (PMID 34454476, 2021). "Subsequently, we analyzed gene expression, survival prognosis, genetic alteration, gene function, immune infiltration and cellular pathways to explore the potential molecular mechanisms of DLGAP5 in different cancers." (PMID 34454476, 2021). "Firstly, we evaluated the expression level of DLGAP5 in 33 types of tumors throughout the datasets of TCGA (Cancer Genome Atlas) and GEO (Gene Expression Synthesis)." (PMID 34454476, 2021). "At present, many reports have been published on the biological function of the DLGAP5 gene in the occurrence and development of cancer." (PMID 32782440, 2020). "DLGAP5 was generally highly expressed in many other cancers, thus playing an important role in the incidence and development of tumors." (PMID 32782440, 2020). "DLGAP5 is associated with cell division and microtubule functions, with research largely focusing on its roles in the cell cycle and cancer proliferation rather than DNA repair processes." (PMID 39777332, 2024). "DLGAP5 is considered an adverse prognostic biomarker in certain diseases, particularly cancer." (PMID 38098472, 2023). "Many studies have identified the relationship between DLGAP5 and cancers." (PMID 37534227, 2023). "Furthermore, it was observed that DLGAP5 also regulated the activity of the JAK2/STAT3 signaling pathway involved in cancer progression and development." (PMID 37958803, 2023). "DLGAP5 is involved in the regulatory mechanisms of cancer through multiple signaling pathways." (PMID 37958803, 2023). "Cells stably transfected with DLGAP5 obtained the characteristics of tumor cells, and silence of this gene could theoretically revert cancer cells to a more normal phenotype." (PMID 35370991, 2022). "DLGAP5, a gene mapped to chromosome 14q22.3, plays an important role in cancer formation." (PMID 36389792, 2022). "A pan-cancer analysis of differential DLGAP5 expression was performed." (PMID 35873473, 2022). "Patients with increased DLGAP5 expression have shown worse prognoses in above cancers." (PMID 35873473, 2022). "DLGAP5 (also called HURP) is a potential cell cycle regulator that may play a role in the carcinogenesis of cancer cells, which has the function of promoting microtubule polymerization and bipolar spindle formation." (PMID 35370991, 2022). "In addition, we also unveiled the statistical pattern that DLGAP5 expression was positively correlated with the predictive infiltration degree of cancer related fibroblasts for TCGA tumors including CESC, ESCA, KIRC, KIRP, LGG, MESO, PCPG and THCA." (PMID 34454476, 2021). "In addition, we investigated the correlation between genetic alteration of DLGAP5 and the clinical feature of survival prognosis in different types of cancers." (PMID 34454476, 2021). "In this part, we set to define the underlying relationship between infiltration status of diverse immune cells and the expression of DLGAP5 in different cancer types of TCGA, the TIMER, CIBERSORT, CIBERSORT-ABS, QUANTISEQ, thus XCELL, MCPCOUNTER and EPIC algorithms were used." (PMID 34454476, 2021). "Moreover, using the Cancer Genome Atlas database, we observed that the expression of the APC substrate genes PTTG1 and DLGAP5 in cancer patients is differentially regulated between normal tissues and tumor tissues, across 24 different types of cancer." (PMID 29954095, 2018). "This interaction between the androgen-regulated cell cycle, DCT and DLGAP5 might also extend to other cancers." (PMID 30341281, 2018). "Biology of the DLGAP5 gene is compatible with the involvement in cancer formation and progression and suggests that the gene and its product may be potential therapeutic targets." (PMID 24349376, 2013).